GAPDH (glyceraldehyde-3-phosphate dehydrogenase)
Diseases named in the same sentence as GAPDH in open-access papers (continued):
Sharing a sentence is not in itself a finding about the gene and the disease.
tumor (continued). "GAPDH acetylation increases its activity and promotes cell proliferation and tumour growth." (PMID 37278715, 2023). "Likewise, tumour growth in vivo is limited by peroxide stress and suppressed when the GAPDH redox switch is disabled in tumour cells." (PMID 37024754, 2023). "Notably, we observed a significantly higher expression of all six ERGs in tumor tissues compared to their adjacent non-tumor counterparts (p < 0.001), with GAPDH exhibiting the highest level of expression." (PMID 37383726, 2023). "Both HK2 and GAPDH are upregulated in many human tumours and serve as drug targets." (PMID 37390227, 2023). "Hence, future studies should address how some tumour cells manage to adapt to an inactivated GAPDH redox switch." (PMID 37024754, 2023). "Similarly, tumour growth in vivo is accompanied by peroxide stress and is strongly suppressed when the GAPDH switch is disabled in tumour cells." (PMID 37024754, 2023). "In the PDX tumour tissue, the expression of both human and mouse GAPDH was observed." (PMID 37957624, 2023). "Our observation that tumors in progression have higher GAPDH gene copies in the AH than progression‐free tumors could be explained by the reduction in the tumor fraction of the cfDNA in treatment‐responsive tumors." (PMID 36148636, 2023). "Simultaneously, the released siRNA targeted and down-regulated glyceraldehyde-3-phosphate dehydrogenase (GAPDH) expression in the tumor to inhibit glycolytic pathway, which interfered with tumor energy metabolism and enhanced Fe2+-induced ferroptosis to kill tumor cells." (PMID 35473696, 2022). "Notably, this alteration was consistent with that observed in the Western blot, i.e., a greatly decreased GAPDH (M.W. 37 kDa) in high-dose (2.0 mg/g) dasatinib-treated tumor." (PMID 36559193, 2022). "RT-qPCR was performed to detect the GAPDH and the tumor marker of glypican 1 gene expression." (PMID 35991837, 2022). "Moreover, GAPDH activity in the transplanted tumor tissues in the HA group significantly decreased compared with that in the PBS group." (PMID 35459092, 2022). "Moreover, decreasing GAPDH caused a downregulation of the gene expression of Snail (SNA), one of the well-known EMT transcription factors involved in tumor progression." (PMID 36559193, 2022). "In addition, S-nitrosylated glyceraldehyde-3-phosphate dehydrogenase activates downstream apoptotic signals and regulates cell and tumour growth." (PMID 36568094, 2022). "As heptelidic acid is expected to act only on tumor cells and immune cells, in particular activated neutrophils, this divergent phenotype indicates that the effect of GAPDH down-modulation on immune cells in the host outweighs its inhibitory effect on tumor growth." (PMID 35205709, 2022). "Tumor cells are highly dependent on the GAPDH-mediated glycolysis pathway for ATP production." (PMID 35459092, 2022). "GAPDH was found to be significantly upregulated at various stages of tumor differentiation." (PMID 35778437, 2022). "Specifically, we identified autoreactive GAPDH and PKM2 clones (multi-cell line cDNA library); these genes play a key role in aerobic glycolysis and apoptosis, while GAPDH expression is also associated with BC cell proliferation and tumor aggressiveness." (PMID 37082114, 2022). "The ncRNA GAPDHP65 (Glyceraldehyde 3 Phosphate Dehydrogenase Pseudogene 65) is related to the already known GAPDH regulation of glycolysis and has a pivotal role in tumor metabolism, which also explains why GAPDH represents an attractive target for therapeutic intervention." (PMID 35456196, 2022). "It was thus unexpected that GAPDH, which was immunoprecipitated with Hsp90ab1, acted as a tumor suppressor as well as an anti-inflammatory protein, although the participation of GAPDH in diverse processes including pro-apoptotic and anti-inflammatory responses has been reported." (PMID 35804814, 2022). "So far, we examined the anti-inflammatory and anti-tumor actions of extracellular GAPDH." (PMID 35804814, 2022).
tumor (continued). "While Hsp90ab1 may assist the stability of GAPDH as a molecular chaperon, we observed that they both served as tumor suppressors to CS cells." (PMID 35804814, 2022). "In addition, we found a glycolytic enzyme glyceraldehyde-3-phosphate dehydrogenase (GAPDH) and several cytoskeletal molecules such as tubulin and cofilin were dramatically decreased after a long-term treatment of the HuCCT1 tumor with a high dose of dasatinib." (PMID 36559193, 2022). "GAPDH activity assay was performed using isolated tumors to assess whether the activity in the transplanted tumor cells decreased after HA administration." (PMID 35459092, 2022). "Notably, the tumor-suppressive effect of extracellular GAPDH was suppressed by silencing L1CAM in SW1353 CS cells, indicating that L1CAM in tumor cells mediated GAPDH-driven anti-tumor action." (PMID 35804814, 2022). "However, PITX2C was rarely expressed, as the values ofΔCt (Ct PITX2C in tumor – Ct GAPDH in tumor) were over 25 in most of HCC cases." (PMID 35765089, 2022). "Binding of the enzyme to Hsp70 could be a factor supporting pro-tumor function of GAPDH and, more significantly, preventing the enzyme molecules from forming cytotoxic aggregates." (PMID 33546324, 2021). "Importantly, these indications of GAPDH relevance for a tumor cell fate were obtained both in cell and animal models." (PMID 33546324, 2021). "Moreover, the high expression of HK1, PFKM, and GAPDH genes correlated with the tumor degree of malignancy." (PMID 34573317, 2021). "Along the same line, ROS can regulate certain metabolic enzymes such as GAPDH, and thus could potentially influence functions and memory subsets of tumor-infiltrating T cells." (PMID 34072260, 2021). "It has been demonstrated that extracellular GAPDH (glyceraldehyde-3-phosphate dehydrogenase) or its N-terminal domain can inhibit the growth of GC cells, and the negative regulation of tumor growth with GAPDH may be a new anti-cancer strategy." (PMID 33953786, 2021). "In conclusion, blocking the chaperonic activity of Hsp70 and its interaction with GAPDH may become a promising strategy to overcome tumor resistance to multiple environmental stresses and enhance existing therapeutic tools." (PMID 33546324, 2021). "Hence, increased GAPDH activity will increase glycolysis rate and promote tumor growth, leading to poor prognosis." (PMID 34650911, 2021). "GAPDH (glyceraldehyde-3-phosphate dehydrogenase) is one of the housekeeping proteins, and the mechanism of its anaerobic conversion to glucose critically regulates tissue regeneration and tumor growth." (PMID 34650911, 2021). "ENO1, GCK, PGK1, and GAPDH are involved in tumor energy metabolism." (PMID 34194463, 2021). "This evidence, both in human tissue and in a mouse model, suggests that targeting GAPDH could be an effective strategy to counteract tumor progression." (PMID 33804240, 2021). "The initiation of GAPDH synthesis may be a protection mechanism for tumor cells to regulate metabolism and improve survival under anoxic conditions." (PMID 34650911, 2021). "A significantly lower (p < 0.0001) total GAPDH signal was detected in Warthin tumor oncocytes." (PMID 32365590, 2020). "Intra-tumor GAPDH-specific Cq variation detected for these tumors may thus be caused by differences in RNA quality." (PMID 31567589, 2020). "GAPDH, cyclophilin, and B-actin are the most common reference gene used for gene expression studies but recent studies have suggested that there is high variability in their expression as a result of hypoxia in tumor tissues." (PMID 33457124, 2020). "If GAPDH is indeed determined to be involved or even required for Warthin tumor development, then GAPDH could represent a therapeutic target that potentially could influence the course of Warthin tumor disease." (PMID 32365590, 2020). "In particular, the spotted appearance of Warthin tumor oncocytes could be ascribed to three different GAPDH phenotypes." (PMID 32365590, 2020).
tumor (continued). "It has been suggested that up-regulation of GAPDH could contribute to an augmented rate of glycolysis in tumor cells and/or maintenance of a transformed phenotype." (PMID 33615312, 2020). "Immunohistochemical analysis of Warthin tumor and normal salivary gland tissues, using a GAPDH specific antibody (clone 0411), revealed a highly distinctive “spotted” GAPDH phenotype, whereas normal oncocytic ductal cells exhibited a more uniform staining pattern." (PMID 32365590, 2020). "Although possible, this appears less likely, since, firstly, different GAPDH antibodies showed comparable staining results after immunohistochemistry, and secondly, GAPDH reduction in Warthin tumor oncocytes was noted not only on the protein but also on the transcript level." (PMID 32365590, 2020). "Similarly, as observed for GAPDH protein levels after digital image analysis, GAPDH mRNA levels also appeared significantly reduced (p < 0.005) in Warthin tumor oncocytes, compared to normal ductal cells." (PMID 32365590, 2020). "Section 13.4 was the only section from tumor 13, from which we could amplify the largest GAPDH fragment; indicating higher RNA quality, however, amongst all the sections of tumor 13 the highest Cq (lowest GAPDH mRNA expression) was measured for section 13.4." (PMID 31567589, 2020). "Growth factors such as insulin and epidermal growth factor could increase the expression of GAPDH in some cell lines by promoting tumor growth." (PMID 33615312, 2020). "However, when using the GAPDH gene as reference, correlations between the growing tumor area and peritumoral area were found only for SCD and SCD5." (PMID 32392704, 2020). "We did not see an association between the raw GAPDH Ct values and node status or other tumor characteristics." (PMID 32493230, 2020). "However, specific studies focusing on the role of GAPDH in Warthin tumor mitophagy will be necessary to clear up this assumption." (PMID 32365590, 2020). "Using U87MG-luc, U87dEGFR and U118MG (grade IV GBM) human cell lines, we examined the effect of progesterone treatments on the expression of Glut1, GAPDH, cytosolic FoxO1 and Phospho-FoxO1 levels, the key players in tumor cell glycolytic metabolism, at 2 and 24 h." (PMID 30700763, 2019). "Thus, the knock-down of GAPDH was found to be sufficient to reduce autophagy and ATP levels in tumor cells." (PMID 31027346, 2019). "Similarly, the expression of GAPDH has been shown to be relatively higher in tumour cells as compared to healthy cells." (PMID 31798003, 2019). "In some cancers, an increase of GAPDH signals tumor progression while in other favors apoptosis." (PMID 30241282, 2018). "Moreover, the expression levels of ACTB and GAPDH were examined in 80 normal and tumour samples from colorectal, breast, prostate, skin and bladder tissues using qRT-PCR, which revealed that these genes were unsuitable as single reference genes." (PMID 29180379, 2017). "Therefore, it is understandable that GAPDH displayed an increasing trend in tumor tissues, which has been proved in several studies." (PMID 27556505, 2016). "Glycation at R399 of PKM2 and changes in the secondary structure of GAPDH complex could be one of the mechanisms by which GAPDH activity is inhibited in tumor cells by MG." (PMID 26911935, 2016). "Here, we report that GAPDH is associated with glucose-6-phosphate isomerase (GPI) and pyruvate kinase M2 (PKM2) in Ehrlich ascites carcinoma (EAC) cells and also in 3-methylcholanthrene (3MC) induced mouse tumor tissue." (PMID 26911935, 2016). "Glycation at Arg399 of PKM2 followed by conformational changes of the GAPDH complexes could be one of the possible mechanisms for MG mediated inhibition of glycolysis in tumor cells." (PMID 26911935, 2016). "An other suggestion comparing the expression of glyceraldehyde-3-phosphate dehydrogenase (GAPDH) and β-F1-ATPase an inverse relationship could be concluded between glycolysis and mitochondrial respiration in various human tumour tissues." (PMID 26869854, 2016).
tumor (continued). "Also, we immunoprecipitated PKM2 in 3MC induced tumor tissue lysate, and probed with antibodies against GAPDH and GPI." (PMID 26911935, 2016). "Association of GAPDH with PKM2 and GPI in tumor cell was validated by immunoprecipitation assay." (PMID 26911935, 2016). "We could confirm this and we can also suggest GAPDH/β-F1-ATPase expression studies in tumour tissue samples by immunohistochemistry based on our Western blot results and its harmony with the metabolic characterisation data." (PMID 26869854, 2016). "GAPDH can interact with both of these enzymes in EAC cells as well as in 3MC induced tumor tissue." (PMID 26911935, 2016). "Furthermore, studies have described GAPDH as a regulator of cell death; other studies have suggested that GAPDH participates in tumor progression and serves as a new therapeutic target." (PMID 25859407, 2015). "Moreover, adding 35 μM TMZ after knockdown of defense genes further lysed tumor sphere-initiating cells, which was not seen in those transfected with siRNA targeting housekeeping gene, glyceraldehyde-3-Phosphate Dehydrogenase (GAPDH)." (PMID 26546412, 2015). "It was reported that overexpressed GAPDH in tumor could bind to active Akt and limit its dephosphorylation." (PMID 26508976, 2015). "Furthermore, the protein levels of β-catenin, PI3K, Akt, TGF-β1, α-SMA, GAPDH, and β-actin (as internal control) in H22 tumor tissues treated in vivo with Brucea javanica oil were detected." (PMID 26508976, 2015). "Moreover, GAPDH acetylation was found in the bacteria, Salmonella enterica, and human tumor cells—shifting the directionality of the enzyme towards the glycolytic direction." (PMID 25374779, 2014). "The results of our analysis proved that the expression of reference genes in our cohort of patients, including only endometrioid histotype and carefully selected and balanced according to their tumor grade, was dependent on tumor grade for B2M, GAPDH, H3F3A, GUSB, HPRT1, POLR2A and UBC." (PMID 25473950, 2014). "ANXA9 expression was calculated as ANXA9/GAPDH expression for each tumor or normal tissue sample." (PMID 25289111, 2014). "In addition to NSCLC, the up-regulation of GAPDH and associated genes, including GACC genes, was observed in other tumor types." (PMID 23620736, 2013). "Thus, inhibiting GAPDH not only affects tumor glycolysis (by blocking the most important energy producing step) but also provides an opportunity to exploit other cytotoxic mechanisms related to it." (PMID 24298908, 2013). "Finally, an in vivo murine model of CLL shows that nanoliposomal C6-ceramide treatment elicits tumor regression, concomitant with GAPDH downregulation." (PMID 24367685, 2013). "GAPDH gene over expression in resected tumor samples is an adverse prognostic factor in NSCLC." (PMID 23988223, 2013). "While it is known that most glycolytic enzymes, including GAPDH, are activated and highly expressed to respond to oxygen deprivation in the tumor, the role of up-regulated GAPDH in NSCLC remains unclear." (PMID 23620736, 2013). "As a key intermediate component of glycolysis, GAPDH could serve an important role in cancer cell development and tumor progression." (PMID 23620736, 2013). "From the clinical point of view the GAPDH HR value found in our patients is interesting; however after tumor stage adjusting, significance was lost, pointing out that GAPDH gene expression had some correlation with tumor stage." (PMID 23988223, 2013). "By comparing our regression results before and after adjusting for tumor stage, it results that HR for GAPDH gene expression was mostly independent from stage in microarray datasets, while in our patient data (IST), after adjusting for tumor stage, HR value was decreased and not significant." (PMID 23988223, 2013). "Targeting tumor-specific GAPDH could be achieved either by targeted-delivery or selective-activation of si/shRNA in the tumor." (PMID 22964488, 2012).
tumor (continued). "We have described earlier a strong and selective inhibitory effect of Bezielle on glycolysis in tumor cells, reflected in a strong reduction of lactate production and activity of glycolytic enzymes glyceraldehyde 3-phosphate dehydrogenase (GAPDH) and lactate dehydrogenase." (PMID 22319564, 2012). "One explanation for the variation may be that the real-time values are normalized to B2M and GAPDH, whose expression may vary between tumor samples." (PMID 22272937, 2012). "In the present study a weak, but in some tumors significant, correlation between FAZA retention and GAPDH expression was observed in both the human and murine tumor model, suggesting that GAPDH is neither an appropriate reference gene nor an ideal hypoxia marker in vivo." (PMID 21306648, 2011). "For each tumour analysed, several epithelial areas (approximatively 5 × 103 cells) were independently captured; stromal areas without infiltrating malignant epithelial cells were pooled to provide a sufficient number of GAPDH copies." (PMID 21179039, 2011). "In the present study we addressed the question whether GAPDH expression is up – or down-regulated by hypoxia in tumor cells of different origin – in vitro." (PMID 19144146, 2009). "Therefore, we can conclude that for GBM gene expression studies, GUSB along with the most frequently utilized internal controls, ACTB and GAPDH, must be considered inadequate for normalizations due to its significant increase in tumor samples." (PMID 19257903, 2009). "The result obtained in HepG2 cells with the GAPDH-specific siRNA is not surprising because some reports indicate that silencing of the gene coding for GAPDH in tumour cells decreases the rate of glycolysis, inhibits cell proliferation and eventually leads to apoptosis." (PMID 19331698, 2009). "PTHrP/GAPDH mRNA ratios were reduced ∼60% in tumours from treated mice at 78 h." (PMID 17533397, 2007). "GAPDH was also widely utilized as a control gene in studies conducted in the last decade to elucidate by RT-PCR the cellular effects of bisphosphonates, not only on osteoclasts or osteoblasts, but also on tumor cells." (PMID 16515701, 2006). "Tumor expression levels were normalized to GAPDH, and expression was then compared to HMECs." (PMID 16168112, 2005). "Threshold cycles (CT's) for p16 and GAPDH of nontumour tissue of UC and UC-associated tumour were obtained by real-time quantitative PCR." (PMID 15292938, 2004). "The cut-off value of the survivin/GAPDH ratio of tumours was decided from the formula (mean+2×s.e)." (PMID 12373603, 2002). "We divided the 57 patients into two subgroups according to their tumour-survivin/GAPDH ratio." (PMID 12373603, 2002). "Additionally, GAPDH overexpression may inhibit apoptotic signaling pathways, thereby promoting tumor cell survival." (PMID 40341308, 2025). "Additionally, GAPDH knockdown boosted Fe2+-induced ferroptosis within tumor cells." (PMID 36837761, 2023). "Tumour-like CAFs (tCAFs): We observed strong differential expression of proliferation-, migration- and metastasis-associated genes (e.g., PDPN, MME, TMEM158 and NDRG1) as well as stress-response-associated genes (e.g., ENO1), and GAPDH in a small cluster (n = 786 cells)." (PMID 37463917, 2023). "We speculate that the malignant phenotype of tumor cells actively releases GAPDH to generate an immunosuppressive tumor microenvironment and explored the impact of miR-4669 overexpression on the extracellular release of GAPDH by Hep3B cells." (PMID 37175615, 2023). "Furthermore, we demonstrated that GAPDH, which is highly expressed in LUAD patients and associated with the tumor immune microenvironment (TIME), may serve as a new diagnostic and therapeutic target." (PMID 36837761, 2023). "Therefore, GAPDH depletion is recommended as a novel strategy to control tumor cells." (PMID 37190124, 2023).